ARL1 (ARF like GTPase 1)
Description:
GTP-binding protein that recruits several effectors, such as golgins, arfaptins and Arf-GEFs to the trans-Golgi network, and modulates their functions at the Golgi complex. Plays thereby a role in a wide range of fundamental cellular processes, including cell polarity, innate immunity, or protein secretion mediated by arfaptins, which were shown to play a role in maintaining insulin secretion from pancreatic beta cells.
Synonyms: ARFL1
Tractability: Small molecule: a structure with a bound ligand is known. Antibody: UniProt places it where antibodies can reach, with high confidence. PROTAC: ubiquitination databases record sites on it; its protein half-life has been measured.
Gene: Protein-coding gene on chromosome 12 (101,393,116 to 101,407,772, reverse strand). Ensembl gene ENSG00000120805.
Subcellular location: Golgi apparatus membrane; Golgi apparatus, trans-Golgi network membrane; Membrane
Subcellular location (Human Protein Atlas): Golgi apparatus
Pathways (Reactome):
Vesicle-mediated transport: Retrograde transport at the Trans-Golgi-Network
Gene Ontology:
Molecular function: enzyme activator activity; GTP binding; GTPase activity; phospholipase D activator activity; protein binding; protein domain specific binding
Biological process: protein localization to Golgi apparatus; retrograde transport, endosome to Golgi; toxin metabolic process; Golgi organization; intracellular protein transport
Cellular component: Golgi apparatus; Golgi membrane; trans-Golgi network; cytoplasm; cytosol; trans-Golgi network membrane; membrane
Genetic constraint (gnomAD): Loss-of-function variants: 8 observed, 15.94 expected, observed/expected ratio (o/e) 0.5, 90% interval 0.29 to 0.91. The upper end of that interval is the gene's LOEUF score, 0.91, which puts it in group 3 of 6, group 1 being the genes least tolerant of losing a copy. Missense variants: 77 observed, 152.12 expected, observed/expected ratio (o/e) 0.51, 90% interval 0.42 to 0.61. Synonymous variants: 45 observed, 50.91 expected, observed/expected ratio (o/e) 0.88, 90% interval 0.69 to 1.13.
Homologues: Orthologues: chimpanzee ARL1 (100% identical), macaque ARL1 (100% identical), dog ARL1 (99% identical), mouse Arl1 (99% identical), guinea pig ARL1 (98% identical), tropical clawed frog arl1 (96% identical), pig ARL1 (95% identical), zebrafish arl1 (94% identical), rat Arl1 (94% identical), Drosophila melanogaster Arl1 (78% identical), Caenorhabditis elegans arl-1 (72% identical). Paralogues in human: ARF5 (57% identical), ARF1 (56% identical), ARF3 (56% identical), ARF4 (56% identical), ARF6 (54% identical), TRIM23 (50% identical), ARL5B (48% identical), ARL5A (47% identical), ARL3 (44% identical), ARL4C (42% identical), ARL14 (40% identical), ARL2 (40% identical), and 18 more.
Diseases named in the same sentence as ARL1 in open-access papers:
ARL1 is named in the same sentence as 12 diseases in open-access papers, as found by Europe PMC text mining. Sharing a sentence is not in itself a finding about the gene and the disease. The quoted sentences say what the papers report.
non-small cell lung carcinoma (2 papers, 2018 to 2022). A group of at least three distinct histological types of lung cancer, including non-small cell squamous cell carcinoma, adenocarcinoma, and large cell carcinoma. "For example, aldo-keto reductase ARL-1 is a potential biomarker for non-small cell lung cancer of smokers and, therefore, may be involved in the pathogenesis of tobacco-related cancers, including HNSCCs." (PMID 30157864, 2018).
candidiasis (1 paper, 2019). Infection with the organism Candida. "Of the five Arf/Arl proteins, Arf2 and Arl1 were shown to be critical for virulence in murine models for candidiasis, and Arl1 was more specifically required for oropharyngeal candidiasis." (PMID 31131089, 2019).
cutaneous melanoma (1 paper, 2024). A primary melanoma arising from atypical melanocytes in the skin. "Moreover, the activation of Golgi Arf-like protein 1 (ARL1) is facilitated by synaptotagmin 1 (SYT1), with ARL1 independently serving as a prognostic determinant for cutaneous melanoma, as higher ARL1 levels correspond to improved prognosis." (PMID 38365684, 2024).
endometrial cancer (1 paper, 2022). Primary or metastatic malignant neoplasm involving the endometrium (mucous membrane that lines the endometrial cavity). "In the case of the ADP-ribosylation factor (ARF)/ARF-like protein (ARL) family, it was observed that a high expression of ARL4D, ARL1, ARF1, and SAR1B in endometrial cancer is associated with better prognosis, while a high expression of ARL4C, ARL2, ARL10, ARL16, and ARL14 promotes worse survival." (PMID 35163161, 2022).
hepatocellular carcinoma (1 paper, 2024). A malignant tumor that arises from hepatocytes. "Aldo-keto reductase 1B10 (AKR1B10), also known as aldose reductase-like-1 (ARL-1), is a secretory protein identified in human hepatocellular carcinoma (HCC) 6-8." (PMID 38370384, 2024).
melanoma (1 paper, 2020). A malignant, usually aggressive tumor composed of atypical, neoplastic melanocytes. "Previously, the presence of a specific ARL1 variant (C148R) was assessed in 351 familial and sporadic melanomas and associated with an increased risk for heterozygous carriers to develop melanoma." (PMID 33072757, 2020).
myopia (1 paper, 2019). "Our microarray data also shows that three of these genes are expressed in human fetal eye tissues (ARL1, KRT12, and PQLC1), of which two (PQLC1 and KRT12) are also expressed in a mouse model of myopia, leading to the hypothesis that these CpG sites may be biologically relevant." (PMID 31100065, 2019).
pancreatic cancer (1 paper, 2024). "In pancreatic cancer cell lines, PKD2 is known to regulate the secretion of MMP-2, MMP-7 and MMP-9 via a multiprotein complex with ARF1 and ARL1, and Arfaptin2,28,76 aiding the invasion of cells in vitro and in vivo." (PMID 38323010, 2024).
cancer (2 papers, 2021 to 2022). A tumor composed of atypical neoplastic, often pleomorphic cells that invade other tissues. "Among the GTPases having a ND in their EN exons, ARL1 gene had the greatest change in the inclusion of ND from pre-natal to post-natal stages and then in cancer." (PMID 36509773, 2022). "Altogether, these results indicate that ARL11 upregulation has a positive impact in CM patients’ overall survival, in part by inducing an immune profile relying on an anti-cancer activity to a greater extent compared to ARL1 expression." (PMID 34502169, 2021).
infection (2 papers, 2017 to 2021). The state of being infected such as from the introduction of a foreign agent such as serum, vaccine, antigenic substance or organism. "We then examined the virulence of Δ/pTetARF2 and arl1/arl1 mutants in two murine infection models, hematogenously disseminated candidiasis (HDC) and oropharyngeal candidiasis (OPC)." (PMID 28192532, 2017). "The dramatic reduction of arl1/arl1 cell infection of the oropharyngeal cavity appears to be niche-specific as the fungal burden in kidney and liver from the HDC mice was similar between this mutant strain and the WT." (PMID 28192532, 2017). "Furthermore, we demonstrated that Arf2 and Arl1 are required for invasive hyphal growth and critical for virulence using different infection assays." (PMID 28192532, 2017).
tumor (2 papers, 2021 to 2023). "However, the bioinformatics analysis performed highlighted the essential role of the tumor microenvironment in the mechanisms related to the prognostic value of ARL1 expression but mostly ARL11 expression." (PMID 34502169, 2021). "Since CM is a highly immunogenic type of tumor, after discovering that ARL1, ARL11, and ARL15 expression may have a significant impact on CM patients’ prognosis, we investigated whether the immune microenvironment could be involved in the mechanisms associated with ARL prognostic value." (PMID 34502169, 2021).
neurodegenerative disease (1 paper, 2022). A disorder of the central nervous system characterized by gradual and progressive loss of neural tissue and neurologic function. "This is interesting since both TMED7 and Arl1 are involved in Golgi vesicle-mediated transport, and its alteration is likely to induce Golgi fragmentation in neurodegenerative diseases, including AD and PD." (PMID 35563596, 2022).